INS (insulin)
Diseases named in the same sentence as INS in open-access papers (continued):
Sharing a sentence is not in itself a finding about the gene and the disease.
diabetes (continued). "Measurements of serum insulin concentrations in patients with diabetes do not add value to clinical practice." (PMID 20618882, 2010). "• Patients with a history of insulin-treated diabetes are more severely ill on admission to the ICU and more likely to have or develop renal failure and to require hemodialysis than patients with no history of insulin-treated diabetes." (PMID 20132545, 2010). "Among White patients with diabetes, 1104 (23.9%) were on no diabetes medications, 2557 (55.4%) on oral glucose-lowering medication, and 954 (20.7%) taking insulin." (PMID 20096107, 2010). "Overall, patients taking insulin developed our pre-specified outcomes more often than patients with diabetes who were not taking any hypoglycemic treatment." (PMID 20096107, 2010). "A well-known condition in which blood glucose levels rise due to deficits in insulin signaling is diabetes, but no common conditions are known in which blood glucose levels decline." (PMID 20414467, 2010). "The results of a single-blind, open-label, single-center, Phase IIa study in 8 T1DM, male subjects (ages 24-41, diabetics for 2-28 years, HgA1C 6.63-8.63%), regularly treated with no-peak insulin was recently presented." (PMID 21059246, 2010). "Engrafted de-ATSCs also showed effectively transdifferentiated into insulin secreting beta cell but we never found beta cell transdifferentiated ATSCs control cells in vivo diabetes animals." (PMID 20161735, 2010). "This type of diabetes is fatal without treatment with exogenous insulin to replace the missing hormone or providing patients with a functional replacement for the destroyed pancreatic β-beta cells, such as pancreas or islet-cell transplantation." (PMID 23554650, 2010). "Using a Cox proportional hazards regression analysis with hospital mortality censored at 28-days as the dependent factor, insulin-treated diabetes was not an independent predictor of mortality." (PMID 20132545, 2010). "Extraordinary advances with insulin monotherapy and understanding of the critical role of the adaptive immune system in the T1D pathomechanism have not translated to diabetes reversal." (PMID 20949090, 2010). "Since untreated diabetics have higher complication rates than regulated diabetics, we chose to treat the rabbits in this study with insulin to increase the survival time of the rabbits, but we did not fully regulate the diabetes." (PMID 21234414, 2010). "In this cross-sectional study of persons without self-reported diabetes mellitus from the Tromsø Study we observed a decline in random casual concentrations of insulin across increasing age groups in men, but not in women." (PMID 21162746, 2010). "Using a large, population-based cohort, our study replicated all previous associations of the GCKR rs780094 polymorphism with metabolic traits, including fasting glucose, insulin, post-OGTT glucose, CRP, and triglyceride concentrations and diabetes prevalence among white participants." (PMID 20661421, 2010). "Subjects comprised 11 type 2 diabetic patients (males: females, 9:2; mean age, 63.9 ± 7.8 years; mean BMI, 24.0 ± 4.0; mean duration of diabetes, 18.0 ± 12.0 years; mean U-CPR, 44.3 ± 37.8 μg/day; mean baseline HbA1c value, 8.4 ± 2.1%; and mean total daily insulin dose, 24.9 ± 8.9 units)." (PMID 20438630, 2010). "Characteristics of the study group on admission to the intensive care unit in patients with and without a history of insulin-treated diabetes." (PMID 20132545, 2010). "Although diabetes is a relatively common comorbidity in critically ill patients - in our study 7% of patients had a history of insulin-treated diabetes - its effects on outcomes have not been extensively studied." (PMID 20132545, 2010). "Type I diabetes, also called juvenile or insulin-dependent diabetes mellitus (IDDM), often manifests in childhood and may result from autoimmune destruction of insulin-producing β-cells of the pancreas." (PMID 23554650, 2010).
diabetes (continued). "Of the 11,071 that report having diabetes that have available data, 817 were diagnosed at or before age 45, are currently on insulin, and are not obese if they were diagnosed over the age of 30." (PMID 20634976, 2010). "Approximately 5% of the diabetics are classified as Type- 1(IDDM), a condition characterized by abrupt onset at any age, destruction of pancreatic islet cells, and dependence on exogenous insulin." (PMID 20922079, 2010). "In addition to a measure of diabetes worries, the IITQ also includes measures of perceptions of insulin therapy, treatment system satisfaction, treatment system preference, and inhaler performance." (PMID 20334647, 2010). "Though to our knowledge there are no published studies of methamphetamine abuse and diabetes, a preliminary report of abnormal glucose tolerance tests and aberrant insulin values in methamphetamine abusers supports this possibility." (PMID 21151866, 2010). "Additional treatments should be added to metformin and lifestyle intervention as diabetes progresses, until patients are receiving an intensive insulin regimen with or without additional oral agents." (PMID 20089006, 2010). "Diabetes patients who moved to a more complex insulin scheme during the study period were not excluded." (PMID 20630062, 2010). "Although it was not unexpected to find lower levels of insulin in the diabetic beta cells, it was surprising to find decreased alpha cell glucagon, especially since one of the hallmarks of diabetes is inappropriately increased glucagon secretion." (PMID 20548773, 2010). "On admission, more patients with a history of insulin-treated diabetes had renal failure and were undergoing hemodialysis than did patients with no history of insulin-treated diabetes." (PMID 20132545, 2010). "Ocular pulse amplitude was not changed by diabetes or insulin in our study which agrees with another study of patients with diabetes who were not subjected to the glucose clamp." (PMID 20573241, 2010). "Of the 363 South Asian patients with diabetes, 56 (15.4%) were on no diabetes medications, 240 (66.1%) were on oral glucose-lowering medication, and 67 (18.5%) taking insulin." (PMID 20096107, 2010). "Some investigations have also demonstrated that uncontrolled diabetes in experimental animal models result in enhanced expression of several cytochrome P450 (CYP) isoforms (CYP2E1, CYP2B, CYP3A, and CYP4A) which can be normalized by insulin therapy." (PMID 19859566, 2009). "Previous work has shown insulin treated patients reported the most negative diabetes impact compared to patients on oral medication or diet only regimens." (PMID 19232113, 2009). "It is possible that the insulin reduction can be attributed to the presence of 1,3-DAG since previous studies emphasized its relationship with serum insulin reduction both in animal models and subjects with type 2 diabetes mellitus." (PMID 19822001, 2009). "Low amounts of free (non-enzymatic) zinc are associated with a decreased insulin content in β-cells and zinc depletion by DEDTC leads to diabetes." (PMID 19492079, 2009). "In a study from 1992, neither insulin nor SU drugs improved hypomagnesemia in diabetes mellitus type 2 patients." (PMID 19946527, 2009). "Development of type 2 diabetes mellitus (T2DM) is characterized by aberrant insulin secretory patterns, where elevated insulin levels at non-stimulatory basal conditions and reduced hormonal levels at stimulatory conditions are major components." (PMID 19607692, 2009). "This is especially true of patients on insulin who get free instructions and monitoring kits at the diabetes centers, unlike patients in primary care." (PMID 19624848, 2009). "In addition to the potential for reducing adiposity, we believe that the improved insulin sensitivity in Mstn−/−, muscle-DN, and constitutively active Akt1 mice suggests that altering metabolism by increasing muscle mass might be a promising strategy for treating diabetes and the metabolic syndrome." (PMID 19295913, 2009).
diabetes (continued). "Diabetes mellitus is a chronic disease that occurs when the pancreas does not produce enough insulin, a hormone that regulates blood sugar." (PMID 19506713, 2009). "Since PPARγ2 is expressed only in adipose tissue, how moderate reduction of PPARγ2 activity in adipose tissue influences insulin sensitivity, diabetes, and other metabolic parameters have been studied but not fully elucidated." (PMID 19390629, 2009). "In case diet and physical exercise are not enough to reach the desired glucose and lipid levels, diabetes treatment must include oral drugs, combined oral therapy and also insulin and even insulin monotherapy (it will be required for 25% of the patients)." (PMID 19825150, 2009). "The failure of streptozotocin induced diabetes to prevent RF entrainment indicates that food induced insulin responses are also not essential for this effect." (PMID 19718444, 2009). "This is particularly evident for human insulin tolerance studies, including the Diabetes Prevention Trial-1, where no human protection was seen from insulin despite positive NOD results." (PMID 20142874, 2009). "For newly diagnosed patients with severely uncontrolled diabetes with catabolism, fasting plasma glucose (FPG) levels above 13.9 mmol/L, random glucose levels consistently above 16.7 mmol/L or HbA1c above 10%, insulin therapy in combination with lifestyle change is the treatment of choice." (PMID 19684847, 2009). "The two OB/D subjects treated with insulin prior to surgery showed improvements post surgery (HbA1c levels dropped from 9.4% and 9.0% at T0 to 7.1% and 7.8% at T3); however insulin therapy was maintained and diabetes was not resolved." (PMID 19936240, 2009). "As part of the Community Diabetes Prevention Project (CDPP) obesity, HbA1c, fasting insulin level, LDL-cholesterol, HDL-cholesterol, triglyceride, HOMA-IR, fasting plasma glucose, microalbumin, waist/hip ratio and VO2max were investigated as early markers of impaired glucose regulation." (PMID 19825145, 2009). "In the final multivariate model, older age, higher BMI, eye problems due to diabetes and cardiovascular comorbidity were also significant; however, diabetes-specific variables such as insulin use, HbA1c and diabetes duration were not." (PMID 19706152, 2009). "This trial will deliver important insights in the effects of self-monitoring of glucose in T2DM patients not using insulin on diabetes related distress and self-efficacy and the role of possible barriers and facilitators underlying its (in)effectiveness." (PMID 19397795, 2009). "None of our patients had insulin-dependant diabetes mellitus, cardiogenic fluid retention, or renal insufficiency." (PMID 20107569, 2009). "Interestingly, while restoring normal BG concentrations in our mice with CTL-induced diabetes (EAD model) rapidly restored normal β-cell replication rates, NOD mouse β-cell proliferation displayed a delayed response to insulin treatment (n = 3 grey triangles)." (PMID 19287497, 2009). "Second, the intensification of diabetes control including the initiation of insulin is not easily done during a regular primary care visit." (PMID 19426530, 2009). "Whilst a diabetes diet was continued, neither further oral antidiabetics nor insulin were required to control diabetes mellitus." (PMID 19918292, 2009). "EPA as well as DHA prevented alloxan-induced diabetes and restored the anti-oxidant status of various tissues to normal range in rats and were shown to be more effective than ALA at lowering plasma glucose and insulin levels and improving insulin sensitivity." (PMID 19664246, 2009). "In type 2 diabetes, the commonest type of diabetes, the muscle and fat cells gradually become nonresponsive to insulin and consequently blood glucose levels rise." (PMID 18959471, 2008). "These patients do not develop diabetes because they are capable of secreting extremely high levels of insulin, probably by increasing their β-cell mass." (PMID 19007436, 2008).
diabetes (continued). "They further stressed the importance of educating the patient at diagnosis about the disease progression of diabetes and the inevitability of needing insulin to maintain good glycaemic control, rather than using insulin as a threat to motivate patients." (PMID 18393965, 2008). "Not only hypertensive patients with diabetes, but also hypertensive patients without diabetes tend to be resistant to insulin stimulated glucose uptake and are hyperinsulinaemic compared with normotensive controls." (PMID 18652658, 2008). "Due to this, these toxins can never be used to human for curing insulin-mediated diseases such as diabetes." (PMID 19330070, 2008). "The five diabetes self-care areas are retained in the DNT15, including three items on nutrition, one item about exercise, three items regarding blood glucose monitoring, one item on oral medications and seven items about insulin administration." (PMID 18452617, 2008). "It was noteworthy that, similar to glucose-stimulated insulin secretion in vitro, serum HCP levels of treated pigs rose within 5 min during IVGTT, comparing favorably to the rise in serum PCP within 1 min of the same animals before diabetes induction." (PMID 18320053, 2008). "Proper control of blood sugar in type 2 diabetes mellitus (T2DM) is not adequate till now in spite of use of well-planned dosage regimens containing oral hypoglycemic agents/insulin or both." (PMID 21264154, 2008). "Overall, oral insulin did not prevent diabetes in all subjects recruited for that arm of the trial; however, a subsequent analysis indicated a delay in diabetes onset in the subgroup of individuals who had high titres of anti-insulin autoantibodies." (PMID 19046214, 2008). "Stress causes a greater derangement in glucose metabolism in patients with diabetes because they are not able to increase insulin secretion as a compensatory response." (PMID 19902035, 2008). "Research to date shows promise for the noninsulin agents as adjuncts to basal and prandial insulin therapy, but their place in the diabetes treatment algorithm has yet to be determined." (PMID 18279520, 2008). "The diabetes advisory system (DIAS) is a nonlinear model of the bloodglucose-insulin system based upon real-life parameters, versus simply BGmeasurements." (PMID 18566688, 2008). "Participants need to have a GAD antibody test results of 101 WHO units or more and a diagnosis of diabetes not requiring insulin at diagnosis." (PMID 18652676, 2008). "Oral antihyperglycaemic therapies potentially delay but do not halt the progressive nature of diabetes; thus insulin therapy eventually will be needed by many patients with type 2 diabetes." (PMID 18393965, 2008). "Neither was significant difference found in diabetes treatment modalities (diet, oral agents or insulin therapy) between the two groups PADs and SHPs (P = 0.46)." (PMID 18937675, 2008). "The designations of type 1 or type 2 diabetes mellitus were not in use at that time and insulin was the mainstay of diabetes treatment." (PMID 18644129, 2008). "Those taking OAAs without insulin claimed a mean [SD] of 1.0 [0.9] test strips per day, while those taking no diabetes medications claimed a mean [SD] of 0.7 [0.6] test strips per day." (PMID 18501012, 2008). "Analysis revealed that variables related to the metabolic syndrome and diabetes were also significantly correlated to insulin levels, albeit to different extents (data not shown)." (PMID 18611252, 2008). "A well-known example is diabetes, which is characterized by elevated blood glucose concentration as a result of no/insufficient insulin production in the pancreas or insulin resistance." (PMID 27873829, 2008). "After adjustment for CRP and insulin, ALT and GGT were still predictive of incident diabetes." (PMID 18533046, 2008). "The rs9402571 SGK genotype associates with increased insulin secretion in lean non-diabetic TUEF/EUGENE2 participants and with lower diabetes prevalence in METSIM." (PMID 18985156, 2008).
diabetes (continued). "Taking diabetes mellitus as a paradigm, we have sought to overcome these limitations by ex vivo electrotransfer of a nonviral insulin expression vector into primary hepatocytes followed by immediate autologous reimplantation in a preclinical model of diabetes." (PMID 18320053, 2008). "Thirteen percent of the sample (weighted estimate) report not to be taking insulin or oral medication and also lack diabetes-related medication in their houses." (PMID 18447930, 2008). "In individuals who do not have diabetes, insulin secretion is modified naturally and continuously by the body's own regulatory systems, depending on the blood sugar." (PMID 17326710, 2007). "In the very early stages of type 2 diabetes (the commonest type of diabetes, also called “adult onset” or “noninsulin-dependent” diabetes”), muscle and fat cells become unresponsive to insulin, so blood-sugar levels increase." (PMID 17760500, 2007). "The spline Cox model selected sex, smoking status (current smoker/ex-smoker), use of angiotensin-converting enzyme inhibitors (ACEI)/angiotensin II receptor blockers (ARB) and spline terms of age, duration of diabetes, TC, HDL-C, blood Hb and insulin use at enrolment (Model 1)." (PMID 18053157, 2007). "While there isn't a specific guideline for patients on less frequent or no insulin, glucose monitoring is useful in helping achieve glycemic goals and should be used with increased frequency whenever modifications are made to the diabetes regimen." (PMID 17448241, 2007). "A study from North Eastern USA showed significantly higher HbA1c in Black women but not Black men with established diabetes, although a significantly higher proportion were insulin-treated." (PMID 17678547, 2007). "Evidence suggests that variations in fasting glucose and insulin amongst those without frank type 2 diabetes mellitus are important determinants of cardiovascular disease." (PMID 17760500, 2007). "Women with previous GDM who later developed diabetes had evidence of lower insulin secretion in response to a glucose load during pregnancy compared to women who did not develop diabetes." (PMID 17640759, 2007). "The aim of this study was to examine the associations of fasting insulin, glucose, and glycated haemoglobin (HbA1c) with CHD and stroke in older women without diabetes (defined as no clinical diagnosis and a fasting glucose less than 7 mmol/l)." (PMID 17760500, 2007). "In the index pregnancy, non-GDM women who later developed diabetes had higher glucose concentrations and a lower mean insulin increment than women who did not develop diabetes." (PMID 17640759, 2007). "Once diabetes has occurred there is no further marked deterioration in insulin resistance; instead, poor insulin secretion (β-cell dysfunction) becomes the main pathological process." (PMID 17760500, 2007). "Further studies are needed to assess clinically relevant threshold values of insulin measures in overweight children and adolescents of different ethnicities that can predict the development of CVD, diabetes and other clinical syndromes in patients both with and without the metabolic syndrome." (PMID 17300718, 2007). "Additionally, 53 SNPs (of which 42 had r2 < 0.80 with each other) had p < 0.01 for incident diabetes AND (all 3 glucose traits OR all 3 insulin traits, OR 2 glucose traits and 2 insulin traits); of these, 36 overlapped with the 736 other SNPs." (PMID 17903298, 2007). "If OADs have failed due to gross dietary noncompliance, addition of insulin therapy is unlikely to achieve glycemic goals without adequate diabetes education." (PMID 17448241, 2007). "When insulin secretion is absent or reduced, or when peripheral tissues fail to respond to insulin, the result is hyperglycaemia leading ultimately to diabetes." (PMID 16464129, 2006). "Oral insulin sensitizing agents with anti-inflammatory activity may provide a duel benefit in CFRD and perhaps serve as an alternative agent for managing diabetes." (PMID 16790062, 2006).